IL1B (interleukin 1 beta)
Diseases named in the same sentence as IL1B in open-access papers (continued):
Sharing a sentence is not in itself a finding about the gene and the disease.
infection (continued). "Moreover, previous studies have demonstrated significant differences in the presence of IL-1β following infection with the EIAV vaccine compared to the virulent strain." (PMID 40522989, 2025). "Indeed, 4 hours post infection, IL-1β and IFN-β were both upregulated in Slc27a1-/- macrophages compared to scrambled controls consistent with their pro-inflammatory phenotype." (PMID 40080408, 2025). "Furthermore, genes associated with inflammaging (IFNα, IL1β, NLRP3, IL6, IL1R and p16) and myeloid lineage (RUNX1, Fil1, CD150, PU.1 and GM-CSF) genes that were upregulated by Omicron PsV infection were downregulated by NGO treatment." (PMID 40025168, 2025). "Additionally, IL-1β expression in human oral epithelium was found to be produced in response to C. albicans infection, while such infection has also been shown to increase TNF-α expression in oral keratinocytes." (PMID 41294483, 2025). "Ibrutinib strongly inhibited IL-1β secretion 24 h and 7 days post-infection." (PMID 41221328, 2025). "When bacterial invasion activates intracellular NF-κB/MAPK signaling pathways, CDK9 is rapidly recruited to the promoter regions of immune genes, initiating the transcription of TNF-α, IL-6, and IL-1β genes and guiding immune cell migration to the infection site." (PMID 41515060, 2025). "IL-1β contributes to the immune response against pathogens by inducing fever, activating lymphocytes, and promoting the infiltration of leukocytes into sites of infection." (PMID 38275805, 2024). "These shifts in CCC pathways were also reflected in single-cell level ligand activities, which showed increased predicted activity of IL1B at the time point of maximal perturbation in all animals but only an increase in CCL2 activity at 4 weeks post-infection in both 170-infected animals." (PMID 38317183, 2024). "In addition, PE_PGRS38 decreased NLRP3-dependent IL-1β release and limited pathogen-mediated inflammasome activity during infection." (PMID 38785795, 2024). "Similarly, hk-CDC-trained/restimulated macrophages showed a significant increase in the percentage of IL-1β + cells after Mtb CDC1551 infection." (PMID 38980014, 2024). "Further, we estimated the production of another pro-inflammatory cytokine, IL-1β at 20 hr post-infection under the knockdown condition of Sirt1 and Sirt3 and observed heightened IL-1β production under knockdown of Sirt1 and Sirt3 in comparison to the scrambled infected control." (PMID 39693143, 2024). "Furthermore, Echo11 can activate the assembly of the NLRP3 inflammasome, leading to the production of IL-1β, which facilitates viral invasion of the brain and subsequent infection of neural cells." (PMID 39767680, 2024). "Indeed, these results are in accord with our published findings that IL-1β levels in the lung at day 2 post infection with SARS-CoV-2 are dependent on GSDMD, but that IL-1β release occurs in a GSDMD-independent manner at later timepoints post infection." (PMID 38553499, 2024). "IL1β and TNFα are important pro-inflammatory cytokines involved in host defense against infection." (PMID 39203441, 2024). "However, infected IL-1β-/- mice treated with CPN1 inhibitor suffered from over 60% mortality, while vehicle-treated IL-1β-/- mice were completely resistant to infection-induced mortality." (PMID 38236896, 2024). "Similarly, IL-1β promotes the recruitment of inflammatory cells to the site of infection and creates a proinflammatory environment favorable for other inflammatory cytokines to act." (PMID 39404402, 2024). "However, infection resulted in the induction of il1b and, to some extent, of tnfa and lymphotoxin a (lta)." (PMID 39102417, 2024). "Furthermore, feeding G. uralensis to yellow catfish induced the activation of TLR-NF-κB and the secretion of IL-1β and IL-8, resulting in enhanced immune function to prevent infection." (PMID 39408233, 2024).
infection (continued). "When V. cholerae was injected alone, mRNA levels of tnfa and il1b incrementally increased throughout infection, mmp9 and cxcl18b levels were highly elevated at 6 hpi before decreasing by 18 hpi, and cxcl8a levels increased by 6 hpi but remained constant through 18 hpi." (PMID 39024393, 2024). "Indeed, activated dendritic cells, macrophages, and NK cells target the site of infection and secrete IL-1β, IL-6, and TNF-α, while activated CD4+ T and CD8+ T cells produce IFN-γ among other inflammatory cytokines that aggravate tissue damage." (PMID 38911850, 2024). "In addition, Fc fused chIL-1β expressing parasite were able to completely eradicate the second round of infection proving the efficacy of IL-1β as an effective molecular adjuvant." (PMID 39221251, 2024). "Hence, we suggest that IL-1β has the potential to not only attract immune cells through chemotaxis, but also stimulate the anti-infection immune response by inducing macrophage ferroptosis." (PMID 39353913, 2024). "As an inflammasome sensor, NLRP12 initiates pyroptosis in response to infections by Yersinia pestis, Plasmodium chabaudi, and Toxoplasma gondii, which results in the secretion of IL-1β and IL-18 and a reduction in the pathogen burden." (PMID 39119293, 2024). "IL-1β is a proinflammatory cytokine that is synthesized by inflammation and secreted by a variety of immune cells; thereby, it is essential for the host’s response to infection and injury." (PMID 38997981, 2024). "However, the ST-ΔtolC+ strain reduced il-1β expression below the ST-WT level at 2 hours post-infection." (PMID 39185619, 2024). "Similarly, Il-18 and Tnf-α showed significant upregulation after 3, 6, and 12 h of infection (p < 0.05), and Il-1β showed significant upregulation after 3 h (MOI = 1:10 and 1:1) and 6 h (MOI = 1:1) of infection (p < 0.05)." (PMID 38927100, 2024). "However, plasma levels of IL-1β were lower in individuals with ongoing PCC who received one or two vaccine doses after infection." (PMID 38316833, 2024). "Infection of Tg(il1β:GFP-F) transgenic larvae allowed the visualization of IL1β expressing cells." (PMID 39102417, 2024). "When macrophages detect microbial products, they initiate the inflammation program, producing chemokines and cytokines (such as IFNS, CXCL1, CCL2, TNFA, CXCl2, IL1B) necessary for recruiting leucocytes and upregulating neutrophil-killing capacity to resolve the infection." (PMID 39298265, 2024). "By contrast, hk-HN trained/restimulated macrophages showed a significantly higher percentage of TNF-α+ cells upon Mtb CDC1551 infection, and a significantly higher percentage of IL-1β + cells after infection with Mtb HN878 or CDC1551, compared to uninfected cells." (PMID 38980014, 2024). "In the triple-depletion model presented here, we found that treatment with M-T807R1/Clodrosome prior to infection resulted in an augmented inflammatory signature, as indicated by increased plasma IL-1β, IFN-γ, IL-10, IL-6, and IL-18 levels in the WT-infected animals." (PMID 38668247, 2024). "IL-1β would induce macrophage transepithelial migration to the site of infection and activation." (PMID 38891741, 2024). "According to these results, obvious IL-1β was present at 3 dpi early during infection and subsequently increased, and IL-1β reached its highest level in the cerebrum of hACE2-C57 mice until death; moreover, no obvious IL-1β was detected during end-stage infection in the lungs of hamsters." (PMID 38256071, 2024). "To summarize, we have shown that estradiol-stimulated CFT073 reduced neutrophil cytotoxicity and increased IL-1β release, which could help the host clear the infection." (PMID 39362931, 2024). "IL-1β expression was significantly down-regulated after infection." (PMID 38698849, 2024). "Aa infection resulted in higher expression of Il-1β compared to infection with Sg or Aa+Sg." (PMID 39125663, 2024).
infection (continued). "The expression levels of interleukin 1 beta (IL-1β), IL-6, IL-8, IL-10, IL-17A, and the interleukin receptor IL-17RA were significantly increased after infection with Yb2 and cYb2ΔsspA and were much greater than those in the brains of control and Yb2ΔsspA-infected ducks at 24 and 48 hpi." (PMID 38594770, 2024). "Despite increased viral load, infection-associated weight loss was significantly reduced after IL-1α (but not IL-1β) blockade." (PMID 38382577, 2024). "Therefore, we assessed the mRNA expression levels of the key inflammatory cytokines TNF, IL-6, and IL-1β following 6 h post-infection with S. anginosus or S. mitis by qPCR and supernatant protein levels following 24 h of infection by ELISA." (PMID 38289109, 2024). "Infection with live wild-type S. aureus induced the release of IL-6 and IL-1β." (PMID 38112465, 2024). "TNF-α and IL-1β are proinflammatory cytokines involved in the induction of inflammatory reactions and both are released primarily by macrophages and monocytes during cell infection and inflammation." (PMID 38478426, 2024). "Previous work has shown that the placental trophoblast constitutively secretes the inflammasome cytokines as IL-1β and IL-18, and the infection with L. monocytogenes can also induce more activation of this pathway, leading to resistance against the bacteria infection." (PMID 38771057, 2024). "In accordance with this, the expression of cytokines CXCL1, IL-36γ, IL-1β, and IL-6, which are thought to be critical in the recruitment of neutrophils to the infection sites and promoting inflammation, were significantly reduced in the CDI + T.mu group compared to the CDI group." (PMID 38565558, 2024). "Inflammatory caspases (caspase-1, caspase-4, and caspase-5 in humans, and caspase-11 in mice) play key roles in the innate immune response against pathogen infection and regulate the production of the pro-inflammatory cytokines: interleukin 1 beta (IL-1β) and IL-18, leading to pyroptosis." (PMID 39625520, 2024). "IL-1α and IL-1β are known to induce an inflammatory response and acute immune response, including the proliferation and recruitment of macrophages and neutrophils to the infection site." (PMID 38533263, 2024). "Furthermore, P1/7 induced NLRP3 inflammasome activation with increased protein expression of NLRP3 and caspase-1 at 9 h post-infection (hpi), leading to the production of inflammatory cytokines, including IL-1β and IL-6." (PMID 39334337, 2024). "These low levels of infection did not cause a significant inflammatory response and are comparable to the levels of IFNγ, IL1β and TNFα in un-infected tissue (Fig. 4A2c)." (PMID 38797844, 2024). "Similarly, the caspase inhibitor Z-VAD-FMK inhibited the cleavage of GSDMD and IL-1β production during P1/7 infection." (PMID 39334337, 2024). "Furthermore, when Glycyrrhiza uralensis was used as a feed supplement for yellow catfish, toll-like receptor-NF-κB signaling was activated and IL-1β and IL-8 cytokine secretion increased, thereby enhancing resistance to infection." (PMID 39273195, 2024). "The p38 signaling transduction pathway (a mitogen-activated protein kinase pathway), plays an important role in modulating the immune response of the host by coordinating the release of pro-inflammatory cytokines such as interleukin (IL-1β) or tumor necrosis factor (TNF) upon infection." (PMID 38674369, 2024). "Tetramerization of the PKM2 monomer/dimer counteracts the LPS-induced increase in glycolysis and modulates the host immune response in vivo by attenuating IL-1β production and promoting IL-10 secretion, leading to an increase in bacterial transmission and impaired infection clearance." (PMID 38755659, 2024). "Importantly, direct pharmacologic inhibition of FAO showed similar effects (suppressed IL-1β and IL-6 expression), with a decrease in pathologic lung damage in animal models of infection." (PMID 39007133, 2024).
infection (continued). "IL-1β has a potent pyrogenic effect: it activates immune cells and promotes the increase in adhesion molecules on endothelial cells to allow the migration of activated immune cells to the site of infection." (PMID 38731826, 2024). "Similar to the protein level, the administration of a high dose of GUANKE reduced the transcription of CCL2 (the gene encoding MCP-1), TNFA, and IL6 on the third day after infection, and decreased the transcription of CCL2, TNFA, IL1B, IL6, and IL17C on the fifth day after infection." (PMID 39431894, 2024). "Additionally, we observed 5.2-fold higher IL-1β expression during infection with the GI.1 genotype compared to the GI.2 infected group (p = 0.04)." (PMID 39273479, 2024). "On the other hand, low expression of IL1B has been reported in the early course of the infection." (PMID 39590591, 2024). "Herein, IL-1β was significantly increased upon infection with LbCen−/− compared to LbWT." (PMID 38543944, 2024). "One explanation might be that the effect of IL-1β may change depending on the stage of the infection." (PMID 39362931, 2024). "This may relate to enhanced duration or severity of infection in disseminated manifestations, as IL-1Ra negatively regulates IL-1β to dampen inflammatory responses." (PMID 38714679, 2024). "The efficiency with which AN_CH_37 treatment suppressed the pro-inflammatory response suggests that Mip supports potent stimulation of IL-1β, TNFα and IL-6, and thus may play an important role in host inflammatory pathology following infection." (PMID 38590438, 2024). "Furthermore, we observed negligible IL-1β secretion in the culture supernatant of primary MBMDM after infection with Tn::icmE." (PMID 38787259, 2024). "Accordingly, after infection, resident macrophages react to infection by releasing a swift burst of IL-1β within the initial hour, whereas neutrophils might maintain IL-1β levels in the subsequent hours." (PMID 38294676, 2024). "Importantly, the attenuation of Del4L was associated with a significant increase in the production of IL-1β and TNF-α early in the infection of pigs." (PMID 38501350, 2024). "However, this response was skewed toward interferon following non-g2g-L2 infection, contrasting with IL-1B dominant responses observed after g2g-L2 infection." (PMID 39530100, 2024). "In this study, we first demonstrated that IL-1β was secreted following the PEDV infection of IPEC-J2 cells and then investigated whether IL-1β secretion during the infection process was mediated by the NLRP3 inflammasome." (PMID 39728983, 2024). "Moreover, treatment with TAK-242 reduced M1_like and slightly increased M2_like macrophages and reduced pro-inflammatory cytokines levels including TNF, IL-1β and IL-6 in ECSparcl1-OE mice on day 20 after infection." (PMID 38762489, 2024). "This suggested that GBS might directly causes ferroptosis of macrophages or some other cells in the early stages of infection, which promotes IL-1β production." (PMID 39353913, 2024). "Our data highlight that this effect is exclusively associated with the infection by HR-HPV genotypes, suggesting that cells infected by LR-HPV could maintain their capacity to generate IL-1β." (PMID 39258253, 2024). "IL-1β and IL-6 are pro-inflammatory markers that play crucial roles in promoting inflammation and facilitating the recruitment and activation of immune cells at infection sites." (PMID 39595561, 2024). "Concurrently, the infection of TOCs with IBV DMV/1639 resulted in a pronounced increase in IL1-β mRNA expression at 3, 6, and 12 hpi (P < 0.05) and IL-6 mRNA expression at 3 and 6 hpi (P < 0.05) compared with both IBV DMV/1639-infected TOCs and non-infected controls." (PMID 39472003, 2024). "Mediating a similar outcome, Nlrp6 (the most downregulated innate gene at 6hrs post-infection; −30.2 fold) acts as a cytosolic sensor in macrophages and mediates the secretion of pro-inflammatory cytokines IL-18, IL-1β and TNF in response to ligand stimulation." (PMID 39344634, 2024).
infection (continued). "Additionally, the protein expression levels of IL-18 and IL-1β in the cell supernatant increased significantly during infection, but decreased after NAR intervention in a dose-dependent manner." (PMID 38256101, 2024). "IL-1β plays an important role in mediating infection, trauma and inflammatory response in the body." (PMID 39980616, 2024). "Moreover, similar to our data, it has been described that il-1β and il-8 can be up-regulated during in vitro infections of SHK-1 cells (salmon head kidney cells) with planktonic EM-90." (PMID 39152462, 2024). "Through various signaling and metabolic pathways, ESAT6 participates in the inhibition of autophagy, in the triggering of necrosis, and in the stimulation of the production of cytokines IL-6, IL-1β, and IL-10 for the creation of a chronic proinflammatory background at a site of infection." (PMID 39591170, 2024). "Although both GBS and IL-1β can cause ferroptosis in macrophages at the initial stage of infection, the ferroptosis caused by GBS may be relatively low, but it activates the release of IL-1β." (PMID 39353913, 2024). "IL-1β could recruit neutrophils to the site of infection to regulate the guts’ intestinal microenvironment." (PMID 39221251, 2024). "Furthermore, a comparison between the post-infection day 10 and healthy control groups with the post-infection day 30 group revealed that the IL-1β mRNA levels in the latter exhibited an average 8.6-fold increase (p < 0.05)." (PMID 39766497, 2024). "We demonstrated that IL-1β was secreted by the human myometrium during labor or in presence of infection and was essential for myometrial efficient contractions as its blockage with an IL-1 receptor antagonist (Anakinra) or a neutralizing antibody completely inhibited the induced contractions." (PMID 38378749, 2024). "Notably, the concentrations of inflammatory cytokines TNF-α, IL-1β, and IL-6 were diminished in the serum and lungs of the LysoPE-treated mice on day five post-infection." (PMID 39390593, 2024). "Pretreatment of IPEC-J2 cells (on insert membranes) followed by a 2 h infection with ETEC resulted in decreased mRNA levels for IL-1β, TLR5 (P < 0.001), and MyD88 (P < 0.05), but increased mRNA levels for IL-8, TNF-α (P < 0.001), and IL-6 (P < 0.01) compared to the control group of IPEC-J2 cells." (PMID 37875712, 2024). "Furthermore, infection with amastigotes also induced IL-1β release by neutrophils, again at lower levels than those infected by promastigote forms of the parasites." (PMID 39250503, 2024). "TNF-α and IL-1β play an important role in the clearance of bacteria and viruses during early infection, but their overproduction could trigger an inflammatory storm, which damages tissues and organs." (PMID 39408834, 2024). "Macrophages activated during infection or injury produce IL1B as an inactive precursor." (PMID 39051372, 2024). "Additionally, the IL-18 level decreased most significantly in the Wh3Δmic1 infection group, and IL-1β also decreased to a certain extent." (PMID 39614314, 2024). "Indeed, outbred pigs immunized with AdHA/NP+Ad-IL-1β showed increased lung pathology following challenge infection, confirming that maintaining a balance of Tregs is crucial for the proper functioning of the immune system." (PMID 39024231, 2024). "In this study, we found that PEDV significantly promoted IL-1β secretion during 12 h of IPEC-J2 cell infection and that the levels peaked at 24 h, indicating that the process of PEDV’s induction of inflammatory factor expression is related to the temporal progression of PEDV infection." (PMID 39728983, 2024). "Our findings suggest that IL-1β SNPs could be used for the early identification of THA and TKA patients with a high risk of infection." (PMID 38790226, 2024). "In addition, NAg can inhibit interferon-mediated immunity in the first days of infection and the subsequent release of proinflammatory cytokines, including IL-6, IL-1β, and TNF-α." (PMID 38535062, 2024).